BAP1 (BRCA1 associated deubiquitinase 1)
Diseases named in the same sentence as BAP1 in open-access papers (continued):
Sharing a sentence is not in itself a finding about the gene and the disease.
tumor (continued). "A recent systematic drug sensitivity screening shows that loss of SETD2 sensitized tumor cells to CDK7 inhibitor, and BAP1 depletion confers vulnerability to inhibitor of DNMT150." (PMID 33423045, 2021). "We selected two BAP1-positive and two BAP1-negative cell lines, of which two were derived from a primary tumor and two from a metastasis." (PMID 34439300, 2021). "BAP1 is an important tumor suppressor in human, expressed and functional across many cell-types and tissues, including those of the immune system." (PMID 33912157, 2021). "The mean difference in the proportion of BAP-1 positive cells between a tumor’s hot spot and cold spot (intratumor heterogeneity) was 41 percentage points (pp, SD 29)." (PMID 33800007, 2021). "Significantly higher LBD tumor (p < 0.001), tumor infiltrating lymphocytes (p = 0.020), higher pathological staging (p = 0.042), and lower nuclear BAP1 stain (p = 0.001) were observed in the metastatic group." (PMID 34771510, 2021). "For instance, multiple PBRM1-driven and VHL monodriver subtypes predominately progress to a solitary metastatic site, whereas ccRCC tumours with multiple clonal drivers, BAP1-driven, and VHL wildtype subtypes show rapid progression to multiple sites." (PMID 34944839, 2021). "Nevertheless, a number of key tumour suppressor genes are frequently affected, including those encoding cyclin-dependent kinase inhibitor 2A (CDKN2A), BRCA1-associated protein 1 (BAP1) and neurofibromin 2 (NF2)." (PMID 34226685, 2021). "Future studies will need to further address these questions, providing insights into potential tumor suppressor functions and other functions of BAP1 within the B cell lineage." (PMID 33912157, 2021). "Specifically, it was found that Bap1 functions as a tumor suppressor gene by inhibiting cystine uptake into cells, thereby rendering them more sensitive to ferroptosis." (PMID 34830866, 2021). "UM tumors often harbor a tumor-initiating mutation in GNAQ or GNA11 with secondary mutation in EIF1AX, SF3B1, SRSF2, or BAP1 that determines metastatic potential." (PMID 34771666, 2021). "The UM92.1 cells were obtained from a massive tumor mass that had destroyed the eye and orbit and led to metastases although this tumor had a disomy of chromosome 3 and expressed BAP1." (PMID 34205625, 2021). "Here, the authors analyse a cohort of Chinese ccRCC cases revealing a mutational signature associated with aristolochic acid exposure, and higher mutational burden and enrichment for BAP1 and SETD2 mutations in ccRCC cases associated with tumor thrombus." (PMID 32029730, 2020). "BAP1 functions as a tumor suppressor through chromatin modulation, transcriptional regulation, cell cycle control, cellular differentiation, and DNA damage repair." (PMID 33585209, 2020). "BAP1 (BRCA1-associated protein) encodes the deubiquitinase (DUB) in the nucleus, a common inactivated tumor suppressor in different cancer cell lines, including uveal melanoma (UVM), renal cell carcinoma, mesothelioma, and cholangiocarcinoma." (PMID 32103754, 2020). "BAP1 belongs to a subfamily of deubiquitinating enzymes that removes ubiquitin from proteins and is a tumor suppressor of BRCA1." (PMID 32101552, 2020). "Good correlation in terms of expression was found for all samples except for MESO 15 for BAP1, which was strongly positive in the original tumor, and slightly positive in the PDX." (PMID 33419364, 2020). "Several studies implicate USP4, USP7, USP6, USP15, USP16, USP42, and USP28 as oncogenes, whereas CYLD, A20, and BAP1 act as tumor suppressors." (PMID 32549302, 2020).
tumor (continued). "BAP1 acts as a tumor suppressor depending on both deubiquitination activity interfered by missense mutations and loss of nuclear localization signal by truncating mutations." (PMID 33585209, 2020). "Preferably, fresh tumor material is used for genetic or transcriptomic analyses or formalin-fixed paraffin-embedded material for BAP1 inactivation testing, which can be determined by protein expression immunohistochemistry." (PMID 32718045, 2020). "One tumor sample pair (T004LE and T288LE), corresponding to primary versus recurrence tumors, showed two BAP1 mutations (K337fs and N157fs) present in both samples." (PMID 32083805, 2020). "Compared with the 3 years AUC values of these established prognostic markers (BAP1 mutant, tumor stage, histological type, subtype and chromosome 3 status), our signature can achieve higher accuracy value." (PMID 33100273, 2020). "EIF1AX mutations are associated with a good prognostic outcome; tumours with an SF3B1 mutation lead to an intermediate prognosis, in contrast to UMs with a BAP1 mutation." (PMID 32998469, 2020). "As a tumor suppressor, BAP1 is critical for promoting DNA repair and cellular recovery from DSB via modulation of H2A ubiquitination." (PMID 33585209, 2020). "Taken together, we conclude that BAP1 has a tumor promoting activity inprostate cancer cells, which is dependent on its Ub hydrolase activity." (PMID 32422649, 2020). "BAP1 is frequently mutated in sporadic clear cell RCC with an incidence rate of 6–17%, which is associated with high tumor grade, rhabdoid/sarcomatoid transformation, and poor clinical outcome." (PMID 33585209, 2020). "While the role of H2Aub in repression versus activation has not been directly tested in these studies, the data suggest that catalytic activity of BAP1 regulates cell death and tumor suppression." (PMID 33230107, 2020). "BAP1 is a tumor suppressor, coding for the nuclear deubiquitinating (DUB) enzyme, which reduces histone 2A ubiquitination (H2Aub) on chromatin." (PMID 32103754, 2020). "Functioning as an oncogenic circRNA, hsa_circ_0052112 enhances tumor cells to invade and migrate by sponging miR-125a-5p that acts as a tumor suppressor, inhibiting BAP1 oncogene." (PMID 32211400, 2020). "BAP1 is a tumor suppressor involved in the repair of DNA double strand breaks, and about 8% of UM patients carry BAP1 germline mutations leading to a loss of function." (PMID 32013269, 2020). "It is likely that other ccRCC-relevant epigenetic tumour suppressors such as BAP1, SETD2, and KDM5C also influence HIF-α transcriptional outputs." (PMID 32807776, 2020). "Recent reports have elucidated the mechanism responsible for the potent tumor suppressor activity of BAP1." (PMID 33065998, 2020). "Tumors with the largest basal diameter above 13 mm exhibited a decline in BAP1, EPM2A, GYG1, GYG2, and PPP1R3C levels, whereas only EPM2A was negatively associated with an increased tumor thickness." (PMID 32751097, 2020). "In order to understand the potential mechanisms of BAP1 function in UM and CM, differential molecular networks of the BAP1 in each tumor were analyzed using the cBioportal-embedded MEMo software." (PMID 32028647, 2020). "In summary, it seems that loss of BAP1 foster genomic instability in tumor pathogenesis, however, the activity of BAP1 promotes tumor cell survival and contributes to therapeutic resistance during irradiation." (PMID 33585209, 2020). "As with BAP1, both ASXL1 and ASXL2 are haploinsufficient tumour suppressors, where mutations can drive pathology as heterozygous mutants alone or in combination with secondary mutations." (PMID 33105797, 2020). "BAP1 inactivation also compromises its ability to promote DNA repair and genomic integrity, although it is currently unclear what is the contribution of BAP1 function in DNA repair for tumor suppression." (PMID 33230107, 2020). "BAP1 functions in theregulation of tumor progression have been largely related to its deubiquitinatingactivity." (PMID 32422649, 2020).
tumor (continued). "All but one tumour have a known UM driver gene mutation (GNAQ, GNA11, BAP1, PLCB4, CYSLTR2, SF3B1, EIF1AX)." (PMID 32415113, 2020). "Loss of BAP1 expression is also associated with an increased infiltration of T cell follicular helper, Treg and CD8+ T cells, suggesting an inflammatory tumor microenvironment." (PMID 31954372, 2020). "An alternative is to apply somatic DNA sequencing—or, if unavailable, BAP1 immunohistochemistry—on tumor material to help decision making." (PMID 31382694, 2019). "To investigate the role of BAP1 independently of chromosome 3 status, we analysed the association between BAP1 and MVD within groups of disomy 3 and monosomy 3 tumours separately." (PMID 31337000, 2019). "Immunohistochemically, BAP1 mutations are characterized by absence of nuclear staining (but commonly cytoplasmic staining), while BAP1 wildtype shows a strong nuclear staining reaction in the tumor cells." (PMID 31635116, 2019). "The association between BAP1 loss and HIF1a expression was corroborated in the TCGA data with multivariate regression including BAP1 and chromosome 3, LBD, or tumour prominence." (PMID 31323773, 2019). "Despite their prominent roles as tumor suppressors, the biological functions of BAP1 and ASXL proteins remain poorly characterized." (PMID 30664650, 2019). "Within the set of D3 tumours, BAP1-negative tumours (n = 3) had a higher expression of HIF1a compared to BAP1-positive tumours (n = 17, p = 0.028)." (PMID 31323773, 2019). "The tumor suppressor function of BAP1 is through its impact on cell cycle regulation, chromatin remodeling and DNA damage." (PMID 30716094, 2019). "BRCA1 associated protein 1 (BAP1) has a histone deubiquitinase activity, which results in tumor and metastasis suppressor activity." (PMID 31216772, 2019). "That BAP1 staining intensities were often higher in cancer cells than in adjacent normal prostate glands suggests that BAP1 usually becomes overexpressed during tumor development." (PMID 31903168, 2019). "It has been shown that the deubiquitinating activity and nuclear localization are both required for BAP1-mediated tumor suppression." (PMID 30716094, 2019). "The massive increase of BAP1 expression with tumor cell proliferation was expected, as BAP1 regulates cell proliferation via deubiquitination of its target protein host cell factor-1 (HCF1), which plays a critical role at multiple stages of the cell cycle." (PMID 31903168, 2019). "Whereas the tumor suppressive role has been attributed to BAP1’s important involvement in DNA double strand breakage repair, there is emerging evidence that BAP1 can also promote tumor growth when it is overexpressed in particular molecular environments." (PMID 31903168, 2019). "A total of 16/18 (89%) of the tumours in the sHLA-positive group had lost BAP1 staining, which was significantly different from the 50/79 (63%) tumours in the sHLA-negative group (p = 0.036)." (PMID 31426578, 2019). "Surprisingly, this tumor showed a BAP1 specific CNV profile, indicating that latter deletion of residues 174–179 has no or little pathogenic effect." (PMID 31426461, 2019). "Further studies are needed to confirm the role of BAP1 status on chemosensitivity of MMe to other drugs used for this tumor such as pemetrexed and platinum-based treatments, as well as potential effects of gemcitabine on BAP1 signal transduction." (PMID 30669483, 2019). "With its gene product being a nuclear ubiquitin carboxy-terminal hydrolase with deubiquitinase activity, BAP1 acts as a tumor suppressor gene with potential pleiotropic effects in multiple tumor types." (PMID 31635116, 2019). "In a range of human tumor types, a cancer-associated mutational hotspot was detected in the PHD domain of MLL3, which mediates association with BAP1." (PMID 31221981, 2019).
tumor (continued). "When examining cytokines, within the group of BAP1-expressing tumours, 8q gain was related to an increased expression of ANGPT2 (p = 0.040) and a decreased expression of VEGF-B (p = 0.022) and VEGF-C (p = 0.026)." (PMID 31337000, 2019). "Tissue spots with normal and cancerous glands usually showed higher BAP1 levels in the tumor cells than in normal glands, although there were also rare cases with lower relative BAP1 levels in the cancer cells." (PMID 31903168, 2019). "To investigate the role of BAP1 independently of chromosome 3 status, we analysed the association between BAP1 and HIF1a/VHL within the D3 and M3 tumours separately." (PMID 31323773, 2019). "As revealed in this study, BAP1 was altered in only two ccRCC specimens, both of which exhibited PD-L1-positive in tumour cells." (PMID 30349421, 2018). "Recent breakthrough studies have discovered a germline mutation/inactivation in BAP1 (BRCA1-associated protein 1), a tumor suppressor gene located on chromosome 3p21.3 in families with a genetic predisposition to develop MPM." (PMID 29666782, 2018). "These in vitro and in vivo functional results thereby highlighted the tumor-suppressive role of BAP1 in ICC." (PMID 30305612, 2018). "(F) A time-course of bioluminescence scores in BAP1-wild-type (wt BAP1) versus catalytically inactive BAP1-mutant (C91A) MM tumour xenografts." (PMID 29345617, 2018). "As a ccRCC tumor-derived mutation in BAP1 disrupted this function in both BAP1-null cells, it suggests that the regulation of ISGF3 is important to BAP1’s tumor suppressor function." (PMID 30355451, 2018). "Clinically, low BAP1 expression was positively correlated with aggressive tumor characteristics, such as larger tumor size, presence of lymphatic metastasis, and advanced tumor node metastasis stage." (PMID 30305612, 2018). "The powerful tumor suppressor activity of BAP1 and its ability to regulate gene × environment interactions in carcinogenesis has been linked to its dual role in the nucleus and in the cytoplasm." (PMID 30455474, 2018). "As expected, BAP1 expression was elevated in tumor cells infected with BAP1 compared with control cells using IHC and western blotting." (PMID 29686263, 2018). "Mechanistically, BAP1 functioned as a tumor suppressor in ICC by inhibiting the extracellular signal-regulated kinase 1/2 and c-Jun N-terminal kinase/c-Jun pathways, and this function was abolished by inactivating mutations." (PMID 30305612, 2018). "Most UMs harbor one Gq pathway mutation (GNAQ, GNA11, CYSLTR2, or PLCB4), one BSE mutation (BAP1, SF3B1, or EIF1AX), and a few recurrent CNAs, in 100% of tumor cells." (PMID 29317634, 2018). "Third, and most important, the subset of BAP1-responsive, Calling Card genes identified here are able to discriminate aggressive, class 2 primary tumor samples from human patients." (PMID 30400891, 2018). "In many cases the protein expression levels of PBRM1, SETD2 or BAP1 correlated with that of STAT2 or IRF9 on the same tumor samples." (PMID 30355451, 2018). "Our results provide novel insights into the biology of BAP1 in cancer tumor suppression and metastasis." (PMID 30400891, 2018). "The tumor-suppressive effects of BAP1 proceeded by antagonizing the activity of the ERK1/2 and JNK/c-Jun signaling pathways." (PMID 30305612, 2018). "BAP1 has been considered a true tumor suppressor and appears to follow a classic Knudson two-hit paradigm." (PMID 30305612, 2018). "The exact role of BAP1 has not been entirely elucidated, earlier reports suggesting that the tumor suppressor function is linked to deubiquitinating BRCA1; however, later studies have indicated that BAP1 is a BRCA1-independent tumor suppressor." (PMID 29946532, 2018).
tumor (continued). "Understanding the roles of these class-discriminating BAP1 genomic targets in the broader context of tumor progression will provide new insights into the cellular mechanisms of UM metastasis." (PMID 30400891, 2018). "Our results showed that the messenger RNA and protein levels of BAP1 were significantly downregulated in ICC versus paired non-tumor tissues." (PMID 30305612, 2018). "BAP1 is a tumor suppressor inactivated in numerous cancers, and ablation of this gene in mice also results in tumor development." (PMID 30349006, 2018). "We cross-referenced our list of 784 highly significant BAP1 genomic target genes to the list of genes from primary tumor expression analysis." (PMID 30400891, 2018). "For example, loss of BAP1 expression in biphasic MPM can only be found in the epithelioid part of the tumor, whereas BAP1 is retained in the sarcomatoid component." (PMID 29848954, 2018). "BAP1 has been shown to bind to the BRCA1 protein enhancing BRCA1-mediated tumor suppression, and is involved in various biological processes including DNA damage response, regulation of the cell cycle and cell growth." (PMID 30477459, 2018). "The growth rate of rTRAIL-treated BAP1-mutant tumours was also significantly suppressed compared with rTRAIL-treated BAP1-wild-type and vehicle-treated tumours (p<0.05) as assessed by longitudinal bioluminescence intensity." (PMID 29345617, 2018). "Somatic truncated BAP1 mutations and aberrant BAP1 expression are more common in sporadic MPM, with a frequency that varies widely among different histologic tumor types." (PMID 29666782, 2018). "At sacrifice rTRAIL-treated BAP1-mutant tumours weighed significantly less than rTRAIL-treated BAP1-wild-type tumours (p=0.020) and vehicle-treated BAP1-mutant tumours (p=0.019)." (PMID 29345617, 2018). "We validated this finding using in vitro, in vivo and ex vivo models supporting the use of BAP1 as a genomic biomarker to identify TRAIL-sensitive MM tumours and a novel stratified approach to treat MM." (PMID 29345617, 2018). "Investigating the levels of cytochrome C in the tumor tissues isolated from animals revealed the downregulation of this protein in the control cells compared with BAP1 expressing tumors." (PMID 29686263, 2018). "Additional sex combs-like (ASXLs) stimulate BAP1 deubiquitinase activity to induce tumor suppression, but how these complexes work in coordination in vivo is unclear." (PMID 30349006, 2018). "(D) Weights of tumour xenografts derived from BAP1-wild-type (wt BAP1) versus catalytically inactive BAP1-mutant (C91A mt BAP1) transduced MM cells following treatment with either vehicle or TRAIL (600 μg per mouse) at the time of sacrifice (day 42) (t-test)." (PMID 29345617, 2018). "BAP1 is a deubiquitylating enzyme that acts as a transcriptional regulator for mammalian development as well as a tumour suppressor." (PMID 28659380, 2017). "We evaluated the contribution of BAP1 expression on tumor cell behavior and therapeutic sensitivity to identify rationale therapeutic strategies." (PMID 28122578, 2017). "Although BAP1 was detected predominantly in the nuclei of tumor cells, weak to moderate expression was also observed in the cytoplasm." (PMID 28404968, 2017). "The BAP1 tumor suppressor is inactivated in numerous cancer types that are outstanding in their molecular diversity and embryonic origin." (PMID 29069806, 2017). "Xenograft tumor experiment observed the effect of miR-31 on EMT, which indicated that overexpression BAP1 plasmid inhibits the tumor growth." (PMID 29159179, 2017). "The tumor suppressor function of BAP1 is dependent both on its nuclear localization and deubiquitinase activity." (PMID 28935764, 2017). "Clear cell RCC (ccRCC) is the most common (∼80%) subtype and is characterized by bi-allelic loss of tumour suppressor genes on chromosome 3p, the most common of which are VHL, PBRM1, SETD2 and BAP1 (refs 15, 16)." (PMID 28489074, 2017).